WNT5A (Wnt family member 5A)
Diseases named in the same sentence as WNT5A in open-access papers (continued):
Sharing a sentence is not in itself a finding about the gene and the disease.
tumor (continued). "Additionally, WNT3A and WNT5A protein levels in tumor mouce xenografts of two groups were analyzed by immunohistochemistry." (PMID 34093821, 2021). "We have previously reported that Wnt5A exhibits a tumor-promoting effect in ovarian cancer." (PMID 33723319, 2021). "Accumulating evidence indicates that Wnt5a exhibits dual effects on tumor progression." (PMID 33754039, 2021). "In particular, Wnt5A-induced ITGAV may be important in increasing tumor cell adhesion, proliferation, and migration contributing to OVC progression." (PMID 33723319, 2021). "Otherwise, the ambivalent character of WNT5A and a tumor‐promoting potential is already known, too." (PMID 33639039, 2021). "In another study, Wnt5a overexpression was also found to decrease cell proliferation and tumor size in HCC, supporting that Wnt5a may serve as a tumor suppressor in HCC." (PMID 33585487, 2021). "HNF4A is regulated by AMPKα signalling and resides upstream of WNT signalling via WNT5A, whose knockdown activity results in cell cycle arrest, cyclin down‐regulation and tumour growth inhibition, findings of which were all consistent the results of the current study." (PMID 34309216, 2021). "Therefore, we inferred that Wnt5a was more likely to play a major role in altering the tumor microenvironment, regulating M2-like TAM polarization, inhibiting tumor immune response, and thus contributing to tumor invasion and metastasis." (PMID 32228612, 2020). "As a matter of fact, for CML, there is evidence that Wnt5a have β-catenin-dependent effects, whereas, in vivo, Wnt5a and DKK1 were described to act as proinflammatory agents and contribute to tumor suppression, hampering the understanding of Wnt5a in this context." (PMID 32751131, 2020). "Wnt5a could also remodel tumor microenvironment by inducing a fibroblast-like or mesenchymal phenotype of adipocytes, which then favors tumor development." (PMID 32140070, 2020). "Wnt5a might also influence the interaction between GC cells and their tumor microenvironment (TME), contributing to a supportive environment for migration and invasion of transformed GC cells." (PMID 32195251, 2020). "Finally, high Wnt5a expression is correlated with poor prognosis, and there is a statistically significant correlation between Wnt5a expression and several clinical parameters, such as lymph node metastasis and tumor depth." (PMID 32195251, 2020). "Similarly, tumor cell proliferation was decelerated in mice injected with Wnt5a-silenced TAMs, as measured by Ki-67 staining." (PMID 32140070, 2020). "Therefore, we believed that Wnt5a was more prone to indirectly facilitate tumor progression through TAMs." (PMID 32140070, 2020). "Moreover, our study showed that Wnt5a+ TAMs promoted tumor cell proliferation and migration, and recruited macrophages infiltration." (PMID 32140070, 2020). "In this work, we also demonstrated that Wnt5a+ TAM was a tumor-supporting TAM subtype." (PMID 32140070, 2020). "Indeed, we observed that Wnt5a was up-regulated in both AB tumor tissue samples and AM-1 cells, consistent with its potential role in the development and progression of AB." (PMID 32742496, 2020). "On the other hand, the available evidence suggests that Wnt5a might be expressed by cells residing in the tumor microenvironment, where feedback mechanisms sustaining Wnt5a secretion and signaling might be established." (PMID 32195251, 2020). "Several studies have shown that Wnt5a is mainly expressed in the tumor stroma, especially in TAMs." (PMID 32228612, 2020).
tumor (continued). "Intriguingly, we also observed that THP-1 macrophages were recruited by TAM-expressed Wnt5a, which could lead to more TAMs infiltration in the tumor microenvironment, thereby resulting in tumor support." (PMID 32140070, 2020). "It indicated that Wnt5a might facilitate tumor progression by affecting the biological function of TAMs." (PMID 32140070, 2020). "WNT5A signaling pathway is critical in regulating tumor genesis and cancer cell invasion." (PMID 33928018, 2020). "Moreover, Leris and colleagues proved that Wnt5a mRNA level was significantly lower in tumour than in normal tissues, particularly in those displaying a more aggressive behaviour." (PMID 33080952, 2020). "Several studies proved that Wnt5a was silenced in most CRC cell lines and specimens due to frequent methylation in its promoter region, and Wnt5a acts as a tumor suppressor in human CRC by interfering with the canonical β-catenin signaling but activating the non-canonical signaling pathways." (PMID 32923386, 2020). "WNT5A has dual effects on the tumor microenvironment; it can promote inflammation and chemotaxis of immune cells through activation of the ROR1/Akt/P65 pathway, as well as stimulating the TLR/MyD88/p50 pathway in myelomonocytic cells, to promote synthesis of the anti-inflammatory cytokine, IL-10." (PMID 33034614, 2020). "The tumor suppressor effects of Wnt5a may be achieved by antagonizing canonical Wnt signaling, resulting in the inhibition of cell growth and migration." (PMID 32650388, 2020). "Another study highlighted the importance of Wnt5a expression following AR inhibition by using single-cell RNA sequencing of circulating tumour cells of metastatic PCa patients, and concluded that a subpopulation of PCa cells expresses non-canonical Wnts to enhance their survival." (PMID 32605008, 2020). "Here, we found that Wnt5a was mainly expressed in TAMs of tumor stroma, especially M2-like TAMs." (PMID 32140070, 2020). "We first report the connection between Wnt5a/CaMKII/ERK/CCL2 axis and biological functions of TAMs in tumor microenvironment, indicating that Wnt5a may be a novel therapeutic target for CRC." (PMID 32140070, 2020). "Furthermore, it has been shown that Wnt5a positive TAMs regulate macrophages infiltration, tumour cell proliferation and migration." (PMID 33080952, 2020). "Furthermore, a higher Wnt5a+CD68+/CD68+ ratio was observed at the tumor invasive front, where there exists M2-like TAMs infiltration." (PMID 32228612, 2020). "Moreover, the expression of miR-139-3p was up-regulated and Wnt5a was down-regulated in tumor tissues from sh-circKIF4A group, compared with that in sh-NC group." (PMID 32268875, 2020). "Moreover, the evidence analyzed above suggests that GC cells have diverse sources of Wnt5a in the tumor microenvironment." (PMID 32195251, 2020). "This WNT5A-mediated senescence-like response may be the mechanism that allows the tumor to evade therapy by undergoing growth arrest." (PMID 32659938, 2020). "RSPO2 can block binding of Wnt5A to Fzd7 receptor to antagonize tumor cell migration." (PMID 31655798, 2019). "It was uncovered that the effects of silenced PITPNA-AS1 on tumor growth and protein levels were abolished after co-transfection with miR-876-5p inhibitor, while the function of miR-876-5p was further attenuated by the silencing of WNT5A." (PMID 31700026, 2019). "Finally, rescue assays were also conducted in vivo to certify the role of PITPNA-AS1/miR-876-5p/WNT5A axis in HCC tumor growth." (PMID 31700026, 2019). "This study also suggested that WNT5A may play a role in creating favorable tumor microenvironments and inducing cancer stem cell properties." (PMID 31382613, 2019). "WNT5A promotes malignant progression in tumor cells and is overexpressed in many types of cancer." (PMID 31655798, 2019). "We have previously shown that Wnt5a affects cytokine production in myeloid and tumour cells." (PMID 31098409, 2019).
tumor (continued). "Gene expression levels measured relative to the adjacent normal cortex sample revealed numerous oncogenic driver genes with >2-fold higher expression in the tumour and clone samples, including genes encoding AURKA/B, CDK4/6, FGFR1, AKT1/2, MTOR, MET, PIK3C2A, WNT5A, SFRP4, and MYC." (PMID 30736342, 2019). "Tumors from the mice injected with miR-876-5p-transfected MGC803 cells were smaller than that derived from mimics control-transfected mice; in miR-876-5p and si-WNT5A or si-MITF group, overexpression of WNT5A or MITF mitigated the inhibitory effects of miR-876-5p on tumor size." (PMID 31171711, 2019). "Immunohistochemistry analysis also revealed that tumours derived from miR-129-5p-overexpressing N3 showed increased miR-129-5p, decreased Wnt5a expression (left), a lower proliferation index as demonstrated by Ki-67 staining and significantly lower levels of CD31 expression (right)." (PMID 29531296, 2018). "Wnt5a expression has been shown to correlate with tumor progression in a variety of cancers." (PMID 29765514, 2018). "Similarly, other investigators have recently demonstrated that decreased expression of WNT5A is a prognostic factor in TNBC patients by showing that patients with reduced expression of WNT5A in their tumor tissue have poor recurrence-free survival." (PMID 30171384, 2018). "Moreover, in the same study, these authors observed WNT5A-positive macrophages in 7 out of 17 primary tumor samples." (PMID 30171384, 2018). "Wnt5a plays an important role in tumour-progressive functions." (PMID 29531296, 2018). "Transwell assay also confirmed the critical role of lncFZD6-FZD6 in WNT5A-induced tumor invasion." (PMID 29535420, 2018). "Moreover, the aberrant activation or inhibition of Wnt5a signaling is emerging as an important event in cancer progression, exerting both oncogenic and tumor suppressive effects." (PMID 28491097, 2017). "We found that pan-Wnt5a protein was highly expressed in over 60% of CRC tumor tissues." (PMID 28859077, 2017). "In addition, we found a higher correlation between Ror2 expression in the tumor and tumor grade and between Ror2 and Wnt5a protein expression in tumor tissue, (Sig." (PMID 28427201, 2017). "Wnt5a/ROR2 signaling is associated with suppression of β-catenin/TCF-dependent transcriptional activity and down-regulated the expression of cyclin D1 in erythroleukemia cells, suggesting its anti-tumor role on cell proliferation." (PMID 29213214, 2017). "We summarized the latest advances on the signaling pathways that are activated by Wnt5a and that pose a conundrum for the rational design of drugs aimed at depleting the CSCs (or tumor initiation cells) within tumors while sparing the function of normal tissues." (PMID 28491097, 2017). "To also explore the effect of non-tumor cell-derived lactate, we added exogenous lactate to the cells and noted an increase in migration that was significantly impaired by recombinant WNT5A in parallel with a down-regulation of the lactate transporter monocarboxylate transporter 1 (MCT1)." (PMID 29069720, 2017). "Besides, in vivo experiment showed that sh-Wnt5a significantly increased tumor volume and tumor weight, and prompted EMT in A549 tumor-bearing mice as compared with the control." (PMID 29054966, 2017). "In addition, statistically significant relationship was found between pan-Wnt5a protein and tumor depth (p = 0.031), tumor metastasis (p = 0.011), and clinical staging CRC tumor tissues (p = 0.001)." (PMID 28859077, 2017). "However, the role of Wnt5a in cancer is still being debated: in certain settings has been described as a tumor suppressor, but it is generally involved as a pro-metastatic factor." (PMID 28320399, 2017). "This might account to the observation that the Wnt5a could exert either oncogenic or tumor suppressive effects in different cancers." (PMID 28491097, 2017).
tumor (continued). "However, this process is bidirectional because Wnt5a can transfer from macrophages into tumor cells via exosomes, which results in the downstream activation of the β-catenin-independent Wnt signaling pathway in target cells." (PMID 28659795, 2017). "On the other hand, Wnt5a may perform as a tumor suppressor in certain cancers by inhibiting β-catenin-mediated transcription via several different molecules, preventing the expression of potential oncogenes." (PMID 28320399, 2017). "In addition, the protein expression levels of Wnt5a isoforms were determined by IHC in the second group of CRC tumor tissues (n = 123)." (PMID 28859077, 2017). "The tumor suppressive function could also be attributed to adhesion promoting function of WNT-5A in certain cell types." (PMID 26514730, 2016). "In addition to tumor-promoting activity, WNT-5A also functions as tumor suppressor in few cancer types." (PMID 26514730, 2016). "Does TAM-derive Wnt5a trigger local inflammation in the tumor microenvironment?" (PMID 27608847, 2016). "WNT5A appears to functions as a tumor suppressor when downregulated." (PMID 26978652, 2016). "A number of diverse biologic processes are regulated downstream of Wnt5a that may contribute to tumor progression." (PMID 27571105, 2016). "We therefore hypothesized that counter-balancing cellular signals may decrease rDNA transcription in order to maintain homeostasis, and that Wnt5a may exert suppressive effects on tumor cell growth and proliferation through such means." (PMID 27500936, 2016). "On the contrary, Wnt5a acts as a tumor suppressor in thyroid tumors." (PMID 26608372, 2016). "Moreover, a significantly lower expression of Wnt5A was observed in tumor samples from the young than the older cohort." (PMID 28027300, 2016). "These suggested that Wnt5a and Ror2 had played a promoting role in tumor metastasis." (PMID 26608372, 2016). "However, the aberrant activation or inhibition of Wnt5a signaling is emerging as an important event in cancer progression, exerting both oncogenic and tumor suppressive effects." (PMID 27571105, 2016). "Wnt5a is particularly interesting as some Wnt5a actions, such as blocking canonical Wnt signaling, might be expected to foster decreased tumor aggressiveness, whereas others might be expected to foster increased aggressiveness." (PMID 27323822, 2016). "The tumor suppressor effects that Wnt5a can exert may be achieved through antagonizing canonical Wnt signaling, resulting in inhibition of cell growth and migration." (PMID 27571105, 2016). "The exact role of Wnt5a in human cancers depends on the tumor context." (PMID 27608847, 2016). "The ability of Wnt5a to inhibit rRNA synthesis and reduce nucleolar size suggests a possible mechanism by which it could constrain tumor growth in vivo." (PMID 27500936, 2016). "In addition it has been recently reported that Fyn mediates Wnt5a/b- and Fz2-induced epithelial-mesenchymal transition and tumor metastasis." (PMID 25622531, 2015). "Thus, it was previously thought that Wnt5a expression contributes to the tumor aggressiveness by enhancing cancer cell invasion and metastasis rather than by promoting cell proliferation in these cancers." (PMID 25622531, 2015). "Similarly, NSCLC samples (35.6%) significantly more frequently showed high Wnt5a expression than matched, adjacent non-tumor tissues (11.19%) (χ2 = 26.8527, P < 0.001)." (PMID 26305508, 2015). "Without knowing whether Wnt5a is secreted it is difficult to determine whether the expression level of Wnt5a in a tumor also indicates the level of Wnt5a signaling activity." (PMID 26029828, 2015). "However, deregulated WNT5a signaling facilitates invasion by multiple tumor types into contiguous tissues." (PMID 26666517, 2015). "The role of ROR2 and Wnt5a in cancer is complex, depending on the tumor type and molecular context." (PMID 26305508, 2015).
tumor (continued). "Since Wnt5a was able to suppress tumor formation and alter the subtype of MMTV-Wnt1 tumors, we tested the hypothesis that Wnt5a expression in these tumors would also result in reduced Wnt/β-catenin signaling." (PMID 25401739, 2014). "This suggested that Wnt5a could act as a tumor suppressor by redirecting the tumor phenotype via antagonism of the Wnt/β-catenin pathway." (PMID 25401739, 2014). "On the other hand, Wnt5a was reported as a tumor suppressor gene in several cancers." (PMID 24999479, 2014). "In summary, the data support a tumor suppressive role for Wnt5a in the mammary gland." (PMID 25401739, 2014). "In addition, Wnt5a is a crucial downstream mediator of tumor cell migration, invasion and proliferation induced by CUTL1." (PMID 24944588, 2014). "In addition, Wnt5a suppressed tumor formation in MMTV-Wnt1 mice and redirected the phenotype of tumors that formed to a less basal-like subtype as indicated by a decrease in K5 and K6 expression." (PMID 25401739, 2014). "Nevertheless, a previous study indicated that Wnt5a plays a key role in malignant progression, although whether Wnt5a exhibits a tumor metastasis-suppressing effect or a promoting effect remains unclear." (PMID 24944588, 2014). "Therefore, our study suggests that Wnt5a is not only involved in inflammation, but also tumor initiation." (PMID 24416340, 2014). "Also, this analysis revealed a direct path from ROR2 receptor and the AP-1 transcriptional sub-network, being the ligand WNT5A (up-regulated in tumor tissues) the activator of this signal." (PMID 24597571, 2014). "The tumor suppressor function of WNT5A has also been suggested in other human cancers." (PMID 24586797, 2014). "Wnt5a suppressed tumor formation as indicated by reduced tumor incidence and increased latency." (PMID 25401739, 2014). "It has been reported that Wnt5a may promote tumor progression through inducing actin reorganization and increasing cell motility via activating the protein kinase C (PKC)." (PMID 24524196, 2014). "We could not formally rule out the possibility that reduced β-catenin signaling in Wnt5a expressing tumors was a consequence of alterations in tumor subtype." (PMID 25401739, 2014). "Wnt5a positive expression appeared as brown granules staining in the cytoplasms of the tumor cells." (PMID 24999479, 2014). "At present, the studies on Wnt5a in cell migration mostly focused on tumor cells." (PMID 23844260, 2013). "Wnt5a has been described as a tumor promoter and a tumor suppressor for different malignancies." (PMID 23947922, 2013). "Intensity of Wnt5a staining positively correlated with the histological grade of the tumor." (PMID 23947922, 2013). "Moreover, depletion of β-catenin reversed the promotion of cell invasion by exogenous Wnt5a, resulting in about 74% reduction in the invasiveness of tumor cells relative to control siRNA-transfected cells." (PMID 24156409, 2013). "As Wnt5a can also activate gene transcription via AP1, SCC tumour development might be associated with an auto-regulatory loop of Wnt5a." (PMID 23505429, 2013). "The second molecule investigated, Wnt5a, has been described as a tumor suppressor." (PMID 23352643, 2013). "Wnt5a, a member of the Wnt family of proteins, has been shown to have contradictory roles in the pathogenesis of many cancers, acting either as tumor suppressor or tumor promoter." (PMID 23947922, 2013). "Intensity of Wnt5a staining also positively correlated with the pathological stage of the tumor." (PMID 23947922, 2013). "Thus, moderate to strong expression of Wnt5a is likely to indicate an aggressive tumor or transformation to an invasive phenotype." (PMID 23947922, 2013). "Using in vitro methods, we also found that Wnt5a may be involved in the migration of malignant UC cells, which could have implications regarding the invasiveness of the tumor." (PMID 23947922, 2013). "Tumor tissues obtained from smokers showed higher Wnt5a expressions than matched normal tissues." (PMID 23349696, 2013).